BRCA1 (BRCA1 DNA repair associated)
Diseases named in the same sentence as BRCA1 in open-access papers (continued):
Sharing a sentence is not in itself a finding about the gene and the disease.
breast cancer (continued). "Examining eight primary tumour samples from hypermethylated t-AML patients, BRCA1 was hypermethylated in three of four breast cancer samples, whereas it was unmethylated in the other four tumours." (PMID 17047656, 2006). "Breast cancer predisposition genes identified to date (e.g., BRCA1 and BRCA2) are responsible for less than 5% of all breast cancer cases." (PMID 16672066, 2006). "Despite decreased DNA repair as the result of mutant BRCA1 expression, this construct produced increased survival in breast cancer cells with DNA double-strand breaks." (PMID 16417649, 2006). "The aim of the present study was to attempt to elucidate a role for RAD51 as a high-risk breast cancer predisposition gene using DHPLC and well-characterised non-BRCA1/2 familial breast cancer patients." (PMID 16762046, 2006). "We expected the decreased DNA repair activity observed in BRCA1 mutant clones to correlate with decreased survival in breast cancer cells exposed to etoposide." (PMID 16417649, 2006). "Our results show that the expression of a mutant BRCA1 construct inhibited cell cycle progression in human breast cancer cell lines, which correlated with decreased sensitivity to double-strand breaks." (PMID 16417649, 2006). "The main focus behind the study is to provide reliable hospital based estimates of genetic influence, and to characterize the nature and prevalence of BRCA1 and BRCA2 germline mutations in early-onset and familial breast cancer cases." (PMID 17018160, 2006). "Previously, we showed that I3C induces BRCA1 expression and that both I3C and BRCA1 inhibit oestrogen (E2)-stimulated oestrogen receptor (ER-α) activity in human breast cancer cells." (PMID 16434996, 2006). "When analysing primary tumour samples of patients with secondary AML, we found BRCA1 hypermethylation only in breast cancer samples." (PMID 17047656, 2006). "Women with a known family history of breast and/or ovarian cancer or mutations in BRCA1 and BRCA2 have a higher lifetime risk of breast cancer than the general population with tumours often occurring at a young age and more often being of a high grade." (PMID 17016484, 2006). "Three tumour samples (three of four breast cancers) were hypermethylated for BRCA-1, whereas in four patients hypermethylation was present in the t-AML sample only." (PMID 17047656, 2006). "In BRCA1 or BRCA2 mutation positive families, the highest risk quintile included almost all the women that developed breast cancer over the comparatively short period of four years of follow-up." (PMID 16507150, 2006). "A significant fraction of sporadic breast cancers (46%) were found to be haploinsufficient for BRCA1." (PMID 16434996, 2006). "BRCA1 and BRCA2 mutations appear to account for a lower proportion of breast cancer patients at increased risk of harboring such mutations in Northern India (6/204, 2.9%) than has been reported in other populations." (PMID 17018160, 2006). "Germline mutations in BRCA1 and BRCA2 confer an estimated 65 and 45% cumulative lifetime risk of developing breast cancer, and an ovarian cancer risk of 39 and 11%, respectively." (PMID 17016486, 2006). "Based on the major role of ATR in cellular response to DNA damage and its multiple interactions with several proteins such as BRCA1, ATR represents an attractive candidate gene to potentially explain a fraction of the remaining breast cancer susceptibility." (PMID 17010193, 2006). "In contrast, we found evidence that increasing parity was protective among both BRCA1 and BRCA2 mutation carriers, and that BRCA1 mutation carriers with two or more offspring had a significantly lower breast cancer risk." (PMID 17187672, 2006). "Breast cancer tissue specimens (n = 262) from 25 BRCA1, 20 BRCA2 and 74 non-BRCA1/2 families were studied on a tumour tissue microarray." (PMID 15642173, 2005).
breast cancer (continued). "Representative areas of all available breast cancer tissue specimens (n = 262) from 25 BRCA1, 20 BRCA2, and 74 non-BRCA1/2 breast cancer families were punched into a tissue microarray." (PMID 15987451, 2005). "Organ-specific differences in epidermal growth factor receptor (EGFR) mutational spectra and frequencies were found in lung cancer and sporadic and BRCA1/2-related breast cancers." (PMID 15841079, 2005). "In summary, women with a BRCA1 or BRCA2 gene mutation and a history of unilateral invasive breast cancer are at increased risk for developing a primary contralateral breast cancer." (PMID 16052221, 2005). "The objective was to detect BRCA1 and BRCA2 mutations in Brazilian patients with breast cancer, so as to establish genetic profiles." (PMID 16389418, 2005). "A large number of distinct mutations, polymorphisms and genetic variants of uncertain significance in the BRCA1 and BRCA2 genes is described in the Breast Cancer Information Core Database (BIC Database)." (PMID 16168118, 2005). "Several studies have compared the characteristics of breast cancers in BRCA1 carriers and in sporadic controls." (PMID 15642173, 2005). "The alteration in exon 20 of BRCA1 was found in a patient who developed breast cancer at the age of 33, and who has a first- degree relative who had also developed the disease." (PMID 16389418, 2005). "Mutations in the two high penetrance genes BRCA1 and BRCA2 are well known, but they account for only 20–30% of the familial aggregation of breast cancer." (PMID 15987455, 2005). "The identification of BRCA1 and BRCA2 mutations is relevant for establishing preventive strategies for women with breast cancer and BRCA mutations, in order to prevent contralateral breast tumors and ovarian tumors." (PMID 16389418, 2005). "As a control group, those authors used age-matched breast cancer patients unselected for family history, whereas in our study we included familial non-BRCA1/2 cancer cases." (PMID 15987451, 2005). "This is the first study to investigate BRCA1 and BRCA2 mutations among Brazilian patients with breast cancer." (PMID 16389418, 2005). "We sought to carry out mutation analysis of FANCD2, BRIP1/BACH1, LMO4 and SFN in a large number of non-BRCA1/2 breast cancer families." (PMID 16280053, 2005). "It is likely that more prevalent low-penetrance genes in combination with environmental exposures modify breast cancer risk in BRCA1 and BRCA2 mutation carriers as well as contribute to breast cancer risk among women in the general population." (PMID 15756256, 2005). "Women with a BRCA1 or BRCA2 mutation and a personal history of breast cancer have high risks of developing contralateral breast cancer." (PMID 16052221, 2005). "In BRCA1, for example, the IVS10-2A->C mutation and the IVS20+1G>A mutation are strongly associated with breast cancer predisposition." (PMID 16280041, 2005). "The 5 year breast cancer risk for this patient as calculated by the BRCAPRO model was 5.7%, and her probability of being a BRCA1 or BRCA2 carrier was 0.47." (PMID 15955237, 2005). "We have also documented previously that efficient predictors for BRCA1 and BRCA2 mutations are early age of breast cancer onset and number of ovarian cancer cases in the family." (PMID 15987451, 2005). "The aim of this study was to detect BRCA1 and BRCA2 mutations in a group of Brazilian patients with breast cancer, in an attempt to establish a genetic profile for this population." (PMID 16389418, 2005).
breast cancer (continued). "The BRCA1 hereditary breast cancer gene has been shown to be involved in DNA double strand break repair." (PMID 15955237, 2005). "Although published reports of NA and FNA have included women at high risk of breast cancer, the proportion of these women who carry a BRCA1/2 mutation is unknown and no conclusions can be drawn regarding the utility of these findings specifically in BRCA1/2 mutation carriers." (PMID 16457692, 2005). "The inheritance of a deleterious mutation in either of the two breast cancer susceptibility genes, BRCA1 or BRCA2, has been associated with a lifetime risk of breast cancer of 45% to 87%." (PMID 16168130, 2005). "In a Finnish study, it was noted that BRCA1 breast cancer patients had a lower survival rate than sporadic cases, BRCA2 patients or patients with non BRCA1/2 related familial breast cancer." (PMID 15996267, 2005). "Palacios and colleagues also compared BRCA1 cases with non-BRCA1/2 cases (cases from families with at least three affected with breast cancer, one of them diagnosed under 50 years of age)." (PMID 15642173, 2005). "Over a thousand BRCA1 single nucleotide sequence variations have been reported in the Breast Cancer Information Core (BIC) database." (PMID 16280041, 2005). "The prevalence of the BRCA1 or BRCA2 mutation found in this study among women with breast cancer and a family history of breast cancer was 13% (4/31)." (PMID 16389418, 2005). "DNA methylation has also been found to be an alternative mechanism of inactivation of BRCA1, a gene that accounts for one half of inherited breast carcinomas." (PMID 16168120, 2005). "Epidemiological studies have demonstrated that BRCA1 and BRCA2 mutations account for less than 20% of the familial aggregation of breast cancer." (PMID 15381934, 2004). "In a previous article, we described the development of a genetic model for familial breast cancer, which takes into account the simultaneous effects of BRCA1, BRCA2 and other genes." (PMID 15381934, 2004). "The ratio of ovarian to breast cancers was on average 0.41 : 1 for BRCA1 families and 0.07 : 1 for BRCA2 families (P=0.015)." (PMID 15026808, 2004). "The pattern of predicted age-specific contributions of BRCA1 and BRCA2 mutations to breast cancer is generally in line with the results of the population studies, where the contribution is highest at young ages at onset and thereafter it decreases." (PMID 15381934, 2004). "Although we did not investigate BRCA gene mutations in all patients in the present study, we performed BRCA1 and BRCA2 gene mutation scanning in 22 patients who had two or more breast cancer patients in their 1st degree relatives." (PMID 15546499, 2004). "The average number of breast cancer cases was comparable (3.70 in BRCA1 and 3.72 in BRCA2 families; P=0.965)." (PMID 15026808, 2004). "As an example, mutations in the BRCA1 and BRCA2 genes account for around 2%–3% of all breast cancer cases, although more prevalent founder mutations in these genes can explain up to about 10% of the disease in some populations." (PMID 15630470, 2004). "In this paper, we have examined the frequencies of the BRCA1 and BRCA2 mutations in unselected series of breast cancer patients, and the FRRs of breast cancer, predicted by the BOADICEA model, since these can be compared with empirical observations." (PMID 15381934, 2004). "Three mutations (BRCA1 IVS5+3A>G, 2626–2627delAA and BRCA2 6503–6504delTT) were found in 41 sporadic patients with early-onset breast cancer and one mutation (BRCA1 E1221X) in two sporadic patients diagnosed with both breast and ovarian cancer." (PMID 15026808, 2004).
breast cancer (continued). "About 5–10% are the so-called familial cases, which can be mainly attributed to deleterious mutations in BRCA1 and BRCA2, and also for the remaining majority of spontaneous breast cancer cases a strong genetic component has been postulated." (PMID 15138483, 2004). "To this end, we have investigated the chemosensitivity of the BRCA1-defective HCC1937 breast cancer cell line, and the BRCA1-competent MCF-7 (hormone-sensitive) and MDA-MB231 (hormone-insensitive) breast cancer cell lines using the MTT assay." (PMID 12698198, 2003). "We investigated the effects of BRCA1 inactivation on drug sensitivity in human breast cancer cell lines." (PMID 12698198, 2003). "The treatment of BRCA1-defective breast cancer cells with Dox or Tax in vitro showed an opposite response." (PMID 12698198, 2003). "It has also been shown that restoration of BRCA1 expression in the BRCA1-defective HCC1937 human breast cancer cell line induces radioresistance." (PMID 12698198, 2003). "The incidence of breast cancer among heterozygous carriers in A-T families, along with the known biochemical interactions between the products of the ATM and BRCA1 genes, has suggested a role for ATM in breast cancer risk." (PMID 14562025, 2003). "Oestrogen and progesterone have both previously been reported to induce BRCA1 expression in breast cancer cell lines containing these nuclear hormone receptors." (PMID 12698194, 2003). "In this study, we have demontrated that BRCA1-defective breast cancer cells show a different sensitivity profile to anticancer drugs such as CDDP, Dox or Tax when compared with BRCA1-competent cells." (PMID 12698198, 2003). "BRCA1 and BRCA2 are breast cancer susceptibility genes: inheritance of one defective copy of either of the two genes predisposes individuals to breast, ovarian and other cancers." (PMID 12838319, 2003). "Perhaps reflecting this, there is some evidence of BRCA1 and BRCA2 mutation carriers having a lower apoptotic response than other breast cancer patients." (PMID 12592359, 2003). "Should this research confirm our preliminary data, evidence will be provided that BRCA1 is a powerful mediator of sporadic breast cancer aggressiveness." (PMID 12698194, 2003). "Two of these are recognised as pathogenic by the Breast Cancer Information Core (BIC) database and the third, BRCA1 5242C>A, although still listed as an unclassified variant, has been recorded 13 times in multicase breast cancer families." (PMID 12698193, 2003). "Elsewhere, the expression of BRCA1 mRNA was induced from 2.5- to 5.0-fold by oestrogen in human breast cancer cell lines MCF7, and the BRCA1 protein was about three-fold." (PMID 12838319, 2003). "Such a model needs to incorporate both the effects of both the known susceptibility genes (BRCA1 and BRCA2) and of other possible breast cancer susceptibility genes." (PMID 11857015, 2002). "The estimated breast cancer incidence rates for BRCA1 increase up to the age group 40–49 years but then decrease, while the incidence rates for BRCA2 mutation carriers increase with age." (PMID 11857015, 2002). "For example, truncating mutations in BRCA1 and BRCA2 confer a high risk of breast cancer, but rarely have somatic mutations in sporadic tumours been reported in either gene." (PMID 12177782, 2002). "In the actuarial outcomes after 10 years’ follow-up, 40% of the 124 BRCA1-patients diagnosed with breast cancer < 50 years had developed contralateral breast cancer, vs 12% of the 40 patients > 50 years at first diagnosis (Plogrank= 0.02)." (PMID 10917555, 2000).
breast cancer (continued). "BRCA1 analysis was conducted in consecutive patients with breast cancer before the age of 40 years (76 women), or whose relatives had breast or ovarian cancer (16 women)." (PMID 10682662, 2000). "Mutations in the genes BRCA1 and BRCA2 are rare in the population and account for a small fraction of all breast cancer in the UK." (PMID 11044354, 2000). "The total proportion of mutations was low (25%), although the percentage of mutations in the BRCA1 and BRCA2 genes was higher, considering the breast and ovarian cancer families and the male breast cancer families respectively." (PMID 10755399, 2000). "We screened the 185delAG and 5382insC (BRCA1) and the 6174delT (BRCA2) mutation in 298 Spanish women with breast cancer." (PMID 10098775, 1999). "Their activity was evaluated by PARP1 inhibition, cardiolipin affinity, and cytotoxicity in BRCA1-deficient HCC1937 breast cancer cells and non-malignant H9C2 cardiomyocytes." (PMID 41594705, 2026). "We present a young woman with breast cancer without a significant family history, and a pathogenic de novo BRCA1 variant." (PMID 41814353, 2026). "Interestingly, MDC1 deficiency also causes PARPi resistance in the context of BRCA1 deficiency as demonstrated using the human retinal pigment epithelium RPE-1 cells and mouse mammary tumor-derived KB1P-G3 cells." (PMID 41408464, 2026). "(B) Correlation of ELF3 and BRCA1 expression levels in TCGA breast cancer datasets." (PMID 41498327, 2026). "In the BRCA1-deficient breast cancer cell line HCC1937, knockdown of ELF3 resulted in a significant increase in spontaneous γH2AX foci, demonstrating that ELF3 deficiency leads to more endogenous DNA damage in BRCA1-deficient breast cancer cells." (PMID 41498327, 2026). "(A) ELF3 expression levels in BRCA1-associated breast cancers and BRCA1-non-associated breast cancers in the TCGA and METABRIC databases." (PMID 41498327, 2026). "Also BRCA1/2 carriers with HR+/HER2- breast cancer seem to benefit from abemaciclib treatment similar to the non-carriers." (PMID 40557948, 2025). "Here, we report a metastatic breast cancer case where a germline BRCA2 mutation was identified via tissue-based gene panel testing, necessitated by prior bone marrow transplantation precluding standard blood-based BRCA1/2 testing." (PMID 40065879, 2025). "We then investigated whether G6PC3 expression correlated with overall survival by analyzing its expression across different breast cancer hormone receptor subtypes with focus on BRCA1/2-intact patients." (PMID 40261702, 2025). "An example of this is when a patient with breast cancer had a germline BARD1 deletion or loss of heterozygosity in the tumor, resulting in a basal-like gene expression profile similar to those observed in cancers associated with BRCA1 germline PVs." (PMID 40805222, 2025). "Results of our analyses suggest that variant rs799905 is not directly associated with an increased risk of breast cancer or BRCA1 promoter methylation, which is generally in line with previously published reports." (PMID 40495194, 2025). "Importantly, the prevalence of BRCA1 promoter methylation in Luminal B breast cancers has been reported to be higher compared to the Luminal A subtypes." (PMID 39392573, 2025).